TOMM40 (translocase of outer mitochondrial membrane 40)
Description:
Channel-forming protein that forms part of the translocase of the outer mitochondrial membrane (TOM) complex essential for the recognition and translocation of cytosolically synthesized mitochondrial preproteins. The TOM complex associates with the ion channel VDAC2 and PINK1 kinase at depolarized mitochondria, this interaction stabilizes PINK1 at the outer mitochondrial membrane and triggers downstream mitophagy by the recruitment of the E3 ubiquitin ligase PRKN. Plays a role in the assembly of the mitochondrial membrane respiratory chain NADH dehydrogenase (Complex I) by forming a complex with BCAP31 and mediating the translocation of Complex I components from the cytosol to the mitochondria.
Synonyms: C19orf1; PEREC1; TOM40; D19S1177E; PER-EC1
Tractability: Small molecule: a structure with a bound ligand is known. PROTAC: ubiquitination databases record sites on it; its protein half-life has been measured.
Gene: Protein-coding gene on chromosome 19 (44,890,569 to 44,903,695, forward strand). Ensembl gene ENSG00000130204.
Subcellular location: Mitochondrion outer membrane
Subcellular location (Human Protein Atlas): Mitochondria; Cytosol
Pathways (Reactome):
Autophagy: PINK1-PRKN Mediated Mitophagy
Protein localization: Mitochondrial protein import
Gene Ontology:
Molecular function: protein binding; protein transmembrane transporter activity
Biological process: protein import into mitochondrial matrix; protein localization to mitochondrion; protein insertion into mitochondrial outer membrane; transmembrane transport
Cellular component: membrane; mitochondria-associated endoplasmic reticulum membrane contact site; mitochondrial inner membrane; mitochondrial outer membrane; mitochondrial outer membrane translocase complex; mitochondrion; TOM complex
Genetic constraint (gnomAD): Loss-of-function variants: 9 observed, 34.45 expected, observed/expected ratio (o/e) 0.26, 90% interval 0.16 to 0.46. The upper end of that interval is the gene's LOEUF score, 0.46, which puts it in group 2 of 6, group 1 being the genes least tolerant of losing a copy. Missense variants: 299 observed, 401.54 expected, observed/expected ratio (o/e) 0.74, 90% interval 0.68 to 0.82. Synonymous variants: 184 observed, 166.16 expected, observed/expected ratio (o/e) 1.11, 90% interval 0.98 to 1.25.
Homologues: Orthologues: chimpanzee TOMM40 (99% identical), macaque TOMM40 (99% identical), dog TOMM40 (96% identical), pig TOMM40 (96% identical), mouse Tomm40 (93% identical), rat Tomm40 (92% identical), guinea pig TOMM40 (89% identical), tropical clawed frog tomm40 (78% identical), zebrafish tomm40 (70% identical), zebrafish tomm40l (68% identical), rabbit TOMM40 (60% identical), Drosophila melanogaster Tom40 (49% identical), and 2 more. Paralogues in human: TOMM40L (53% identical).
Diseases named in the same sentence as TOMM40 in open-access papers:
TOMM40 is named in the same sentence as 79 diseases in open-access papers, as found by Europe PMC text mining. Sharing a sentence is not in itself a finding about the gene and the disease. The quoted sentences say what the papers report.
Alzheimer disease (57 papers, 2012 to 2025). A progressive, neurodegenerative disease characterized by loss of function and death of nerve cells in several areas of the brain leading to loss of cognitive function such as memory and language. "TOMM40 has been linked to the development of Alzheimer’s disease pathogenesis due to its connection with mitochondrial dysfunction." (PMID 40863490, 2025). "TOMM40 genetic variants are believed to increase the risk of Alzheimer’s disease (AD) in different populations." (PMID 36835494, 2023). "Although polymorphisms encoding TOMM40 have been shown to be associated with an increased risk of late-onset Alzheimer’s disease, further studies are needed to elucidate the function and mechanism of TOMM40L in the future." (PMID 36544763, 2022). "Intronic polymorphic TOMM40 variants increasing TOMM40 mRNA expression are strongly correlated to late onset Alzheimer’s Disease." (PMID 36517509, 2022). "Because of this, strong correlations between nucleotide polymorphisms of TOMM40 and Alzheimer’s disease have commonly been attributed to the transposition of APOE/TOMM40 regulatory elements." (PMID 36517509, 2022). "An example is variant rs2075650 (a locus sometimes attributed to gene TOMM40), which has been linked to Alzheimer’s disease in seven GWASs." (PMID 32948767, 2020). "The TOMM40 protein is a component of the mitochondrial membrane and mutations appear to contribute to risk of Alzheimer's disease and other aging phenomenon." (PMID 31622379, 2019). "TOMM40 polymorphisms are therefore very interesting targets to study in association with human disorders such as Alzheimer’s disease." (PMID 25311932, 2014). "In humans, a polymorphism encoding this gene complex (TOMM40) has been associated with an increased risk of developing late-onset Alzheimer disease (AD), although recent results conflict with several reports." (PMID 23573274, 2013). "The translocase of the outer mitochondrial membrane 40 (TOMM40) gene has been proposed as a genetic risk factor in Alzheimer disease (AD)." (PMID 24146538, 2013). "We previously discovered that a polymorphic, deoxythymidine-homopolymer (poly-T, rs10524523) in intron 6 of the TOMM40 gene is associated with age-of-onset of Alzheimer's disease and with cognitive performance in elderly." (PMID 22359560, 2012). "There is accumulating evidence that the poly-T locus in TOMM40 is associated with progression to Alzheimer's disease (AD)." (PMID 22359560, 2012). "However, elevated TOMM40 RNA levels in the brains of Alzheimer’s disease patients have been associated with decreased mitochondrial DNA copy number and membrane potential under oxidative stress." (PMID 40003995, 2025). "From the literature reviews, we can see that NECTIN2 has inflammatory roles in the brain, TOMM40 causes neuro-inflammation and Alzheimer’s disease and APOC4-APOC2 may affect the TOMM40-APOE-APOC2 axis, related to Alzheimer’s disease." (PMID 38672162, 2024). "Several studies have reported that translocase of the mitochondrial outer membrane 40 (TOMM40) gene may increase the risk of developing Alzheimer's disease (AD)." (PMID 38285218, 2024). "It is also highly likely that Alzheimer’s disease is associated with polymorphisms in the OMM protein Tomm40 gene, which may be associated with age as an important risk factor for triggering Alzheimer’s disease." (PMID 34604240, 2021). "Increasing evidence suggests that the Translocase of Outer Mitochondria Membrane 40 (TOMM40) gene may contribute to the risk of Alzheimer’s disease (AD)." (PMID 34204109, 2021). "In hypothesis-driven tests, there was significant association between general cognitive function and four genes previously associated with Alzheimer's disease: TOMM40, APOE, ABCG1 and MEF2C." (PMID 25644384, 2015). "The GG genotype and the G allele were significantly more frequent in the patient group, supporting the potential of TOMM40 rs2075650 genotyping as a biomarker for Alzheimer’s disease onset." (PMID 41465142, 2025).
Alzheimer disease (continued). "A study on late-onset Alzheimer’s disease focusing on protein–protein network interactions revealed eight genes with strong associations: APOE, SORL1, APOC1, CD33, CLU, TOMM40, CNTNAP2, and CACNA1C." (PMID 39228919, 2024). "Several variants mapped to PVRL2, TOMM40, LCMT1, and RAB3GAP1 genes previously associated with Alzheimer disease." (PMID 38291454, 2024). "TOMM40, a high confidence multivariate longevity gene, was the most significant gene in a recent Alzheimer’s disease TWAS41 and influences age-related memory performance." (PMID 37076473, 2023). "All three of the replicated genes have been previously associated with clinically diagnosed Alzheimer’s disease (SORL1, TREM2, and TOMM40/APOE)." (PMID 36750708, 2023). "EXOC3L2 has not been previously reported to modulate dyslipidemia but EXOC3L2, APOE, TOMM40, and PVRL2 are reported to be Alzheimer’s disease-susceptibility genes." (PMID 32727492, 2020). "Genetic variations in apolipoprotein E (APOE) and proximal genes (PVRL2, TOMM40, and APOC1) are associated with cognitive function and dementia, particularly Alzheimer’s disease." (PMID 29739406, 2018). "The translocase of outer mitochondrial membrane 40 (TOMM40), which lies in linkage disequilibrium with the apolipoprotein E (APOE) gene, has been implicated in Alzheimer’s disease (AD)." (PMID 30517207, 2018). "An intriguing gate-keeper of this mitochondrial import process is TOMM40, the gene for which is located within the APOE block of linkage disequilibrium that confers susceptibility to Alzheimer's Disease, as discussed later." (PMID 27242399, 2016). "Recently, the rs2075650 single nucleotide polymorphism in the translocase of outer mitochondrial membrane 40 homolog (TOMM40) gene was identified as a risk factor for AMD and Alzheimer disease." (PMID 24146538, 2013). "Several studies have identified TOMM40 in Alzheimer’s disease." (PMID 41498025, 2025). "A growing body of evidence suggests that TOMM40, a gene located next to APOE on chromosome 19, may influence the risk of developing Alzheimer’s disease (AD)." (PMID 37718796, 2023). "Despite the weight of genetic evidence linking TOMM40 dysregulation to Alzheimer’s Disease, the cellular pathways responsible remain unclear." (PMID 36517509, 2022). "Indeed, translocase of outer mitochondrial membrane 40 (TOMM40), which lies in linkage disequilibrium with the APOE gene, has previously been reported to be associated with Alzheimer’s disease." (PMID 34943074, 2021). "The genomic region chr19:44,902,730–44,915,006, comprising the whole APOE gene as well as its promoter and small parts of TOMM40 and APOC1, was selected as a target region because it includes several SNVs and haplotypes previously linked to Alzheimer’s disease and other age-related diseases." (PMID 33271988, 2020). "Amongst other established GWAS loci, there was evidence suggesting that expression of the TOMM40 gene and DNA methylation may play a role in Alzheimer’s disease." (PMID 30820025, 2019). "To date, promising research suggests that variants of TOMM40 or BIN1 may be relevant for assessing the risk of Alzheimer’s disease; however, they have not yet been recognized as standard diagnostic criteria for the condition." (PMID 41465142, 2025). "For instance, accumulated amyloid precursor protein (APP) within mitochondria from individuals with Alzheimer's disease interacts with the protein channel components of both outer and inner membranes: TOM40 and TIM23 (TOMM40 and TIMM23)." (PMID 37303235, 2023).
Alzheimer disease (continued). "Our results add to the growing body of evidence that TOMM40, in the absence of APOEɛ4, may contribute to cognitive changes with aging and dementia and support the view that mitochondrial function is an important contributor to Alzheimer’s disease risk." (PMID 37718796, 2023). "For Alzheimer’s disease, allelic heterogeneity was observed in the genomic locus containing NECTIN2, TOMM40, APOE and APOC1, which has been reported before and reflects the fact that different APOE haplotypes ε2, ε3 or ε4 can be risk factors or protective factors for Alzheimer’s disease." (PMID 34326310, 2021).
Parkinson disease (11 papers, 2016 to 2025). A progressive degenerative disorder of the central nervous system characterized by loss of dopamine producing neurons in the substantia nigra and the presence of Lewy bodies in the substantia nigra and locus coeruleus. "Mitophagy plays a key role in Parkinson's disease pathogenesis, therefore variation in TOMM40 is also a plausible means by which polymorphism in the ApoE/TOMM40 linkage disequilibrium block can have a causal role in AD." (PMID 27242399, 2016).
dementia (10 papers, 2015 to 2025). Loss of intellectual abilities interfering with an individual's social and occupational functions. "As it relates to dementia, TOMM40 is a well-established risk gene for late-onset AD and resides near APOE, and differential TOMM40 expression has been demonstrated in the brain." (PMID 39766777, 2024). "Dozens of significant dementia-associated genes have been identified, including APOE, APOC1, and TOMM40." (PMID 38542318, 2024). "We observed association of general cognitive function with four genes previously associated with AD or neuropathological features of AD and related dementias (TOMM40, APOE, MEF2C and ABCG1)." (PMID 25644384, 2015). "However, a case–control GWAS (with family history of dementia as exclusion criteria in cases) with 9 of 13 significant SNPs in the APOE region implicated APOE, APOC1, TOMM40, and NECTIN2 in the prediction of clinical diagnosis of AD in the Chinese population." (PMID 40352683, 2025). "In order to develop a deeper understanding of TOMM40 genetic variants in individuals without dementia, we conducted a systematic review of published research studies that examined the role of TOMM40 SNPs in the aging process." (PMID 35964003, 2022). "Furthermore, NECTIN2 gene is located in a major dementia locus along with TOMM40 and APOE genes." (PMID 38408961, 2024). "Along with TOMM40 and APOE4 on the same chromosome, NECTIN2 has been shown to be involved in longevity and dementia." (PMID 38408961, 2024).
cognitive decline (8 papers, 2018 to 2025). "These were both associated with cognitive decline according to GWAS and affect the expression of shared TOMM40 targeted gene, encoding the channel-forming subunit of the TOM translocase complex that is essential for import of protein precursors into mitochondria." (PMID 29745862, 2018). "Additionally, the G allele of rs2075650, associated with reduced TOMM40 expression, may impair mitochondrial resilience to Aβ toxicity, accelerating cognitive decline." (PMID 40191788, 2025). "TOMM40 and SORCS1 were associated with both amyloid and tau CSF biomarkers, while BCHE was associated with cognitive decline." (PMID 37629144, 2023). "We associated TOMM40 and SORCS1 with both amyloid and tau pathologies, whereas BCHE was associated with cognitive decline." (PMID 37629144, 2023). "For example, a study highlights the involvement of APOE and its neighbouring genes (TOMM40, NECTIN2, BCAM) in AD and cognitive decline, partly reinforcing our findings of shared genetic susceptibility between vascular calcification and AD-related traits." (PMID 40149595, 2025).
Cognitive impairment (6 papers, 2017 to 2025). Abnormal cognition is characterized by deficits in thinking, reasoning, or remembering. "APOE on 19q13.32, APOC4-APOC2 on 19q13.32, and TOMM40 on 19q13.32 were previously shown to be associated with AD and cognitive impairment." (PMID 39975850, 2025). "We have demonstrated that folate-deficient mice which exhibit cognitive impairment also have an increase in Tomm40 expression further implicating this gene." (PMID 33282900, 2020). "TOMM40 encodes for a beta-barrel protein that ultimately forms a central pore in the outer mitochondrial membrane, and much like APOE, genetic variants of TOMM40 are linked to cognitive impairment and neurodegenerative disease." (PMID 29460123, 2018). "Some studies have proposed that the translocase of the outer mitochondrial membrane 40 (TOMM40) plays a role in regulating the entry of Aβ into the mitochondria through the Tom40 outer membrane pore, underscoring its role as a potential target for the treatment of cognitive impairment." (PMID 39286235, 2024).
ovarian carcinoma (5 papers, 2020 to 2025). A malignant neoplasm originating from the surface ovarian epithelium. "TOMM40 overexpression at both the transcriptional and translational levels in ovarian cancer has been shown to correlate with increased cell proliferation, migration, and invasion." (PMID 34204109, 2021).
dyslipidemia (4 papers, 2016 to 2024). "TOMM40 has been identified in genome-wide screens for dyslipidemia and carotid artery disease." (PMID 27060904, 2016).
delirium (3 papers, 2022 to 2026). A disorder characterized by confusion; inattentiveness; disorientation; illusions; hallucinations; agitation; and in some instances autonomic nervous system overactivity. "AD poses a risk for delirium, probably mediated by shared genetic variants NECTIN2 and TOMM40 that impact acetylcholine pathways." (PMID 41630310, 2026). "Nonetheless, our findings suggest newly identified genes (for example MS4A4A, CR1 and TOMM40) that may be of relevance to future delirium research and therapeutic targets investigations." (PMID 41286463, 2026).
Type II diabetes (3 papers, 2018 to 2020). "For instance, TOMM40 is a shared disease-associated gene between AD and Type II diabetes." (PMID 30666269, 2018).
breast carcinoma (2 papers, 2022 to 2025). "However, among the DE mRNAs whose expressions were upregulated in breast cancer tissues, TOMM40 was highly expressed in TNBC compared to that seen in other molecular subtypes, and EPN3 was expressed lower in TNBC than in other molecular subtypes." (PMID 36294892, 2022). "A series of experimental validations have shown that USP30 can interact with TOMM40, and USP30 deubiquitinating TOMM40 promotes the development of breast cancer." (PMID 40918504, 2025).
coronary artery disease (2 papers, 2018 to 2020). "However, its locus has been extensively linked to coronary artery disease (neighboring genes are APOE, APOC1, and TOMM40)." (PMID 29527417, 2018).
endometrial carcinoma (2 papers, 2024). A malignant tumor arising from the epithelium that lines the cavity of the uterine body. "The pan-cancer analysis revealed an association between elevated TOMM40 expression in Uterine Corpus Endometrial Carcinoma and an unfavorable prognosis, while increased TOMM40 expression in six tumor types was linked to a favorable prognosis." (PMID 39060752, 2024). "A systematic study characterizing mitochondrial autophagy in endometrial cancer, to predict tumorigenesis and prognosis, showed that the endometrial cancer oncogene TOMM40 promotes cancer progression through mitochondrial autophagy-related pathways." (PMID 38711526, 2024).
hippocampal atrophy (2 papers, 2019 to 2025). "Our findings provide evidence that TOMM40 and APOC1 as candidate genes may promote the application of hippocampal atrophy rate as an early biomarker for predicting cognitive progression and detecting disease trajectories." (PMID 31760383, 2019).
osteosarcoma (2 papers, 2024). A usually aggressive malignant bone-forming mesenchymal neoplasm, predominantly affecting adolescents and young adults. "Meanwhile, wound healing showed that si-TOMM40 and si-FH reduced the invasive ability of osteosarcoma cell lines." (PMID 38285218, 2024). "Western blot further demonstrated a higher expression of TOMM40, FH in the metastatic group of osteosarcoma patients." (PMID 38285218, 2024). "We finally found that TOMM40 and FH can significantly promote osteosarcoma metastasis, and the pro-metastatic ability of TOMM40 and FH was verified by in vitro experiments." (PMID 38285218, 2024). "Given that TOMM40 and FH are upregulated in the osteosarcoma metastasis group, we further analyzed the pan-cancer characteristics of TOMM40 and FH." (PMID 38285218, 2024). "However, there are few studies on the mechanism of action of TOMM40 and FH in osteosarcoma." (PMID 38285218, 2024). "According to the Western blot results, the expression of TOMM40 and FH was higher in the metastatic tissues of osteosarcoma than in the non-metastatic group." (PMID 38285218, 2024). "qPCR results showed significant differences in the expression of TOMM40 and FH mRNA in the metastatic and non-metastatic groups of osteosarcomas." (PMID 38285218, 2024).